CCL5 (C-C motif chemokine ligand 5)
Diseases named in the same sentence as CCL5 in open-access papers (continued):
Sharing a sentence is not in itself a finding about the gene and the disease.
periodontitis (continued). "For example, the concentration of CCL5 in gingival crevicular fluid (GCF) has generally been shown to be higher in patients with periodontitis than in healthy subjects and higher in affected areas than in unaffected areas." (PMID 38139161, 2023). "Bacteria are the factor responsible for the increased expression and production of CCL5 in gingival cells in patients with periodontitis." (PMID 38139161, 2023). "Lipopolysaccharide induced the expression of CCL5 in CD14 + sorted cells from gingival crevicular fluid of periodontitis patients." (PMID 36414950, 2022). "Of note, although human periodontitis was associated with elevated IL-ß expression and MDSC recruitment, LPS appreciably only induced CCL5 and CCL2 in human gingival fibroblasts." (PMID 31685946, 2020). "The degree of suppression of IL8, IL1B, CCL2, CCL5, MMP3, and COX2 caused by I-BET151 or JQ1 in P. gingivalis-infected GFs from periodontitis patients was comparable to that observed in healthy donor GFs." (PMID 31114581, 2019). "Even after therapy, persons with periodontitis were found to continue producing high levels of RANTES/CCL5." (PMID 24151615, 2013). "Cell cultures of whole blood from persons with periodontitis produce higher levels of RANTES/CCL5 when stimulated with LPS compared to cultures from control individuals." (PMID 24151615, 2013). "CCL5 is involved in the pathomechanism of periodontitis; however, studies on the molecular mechanisms and significance of CCL5 in periodontitis are insufficient to understand the action of CCL5 in this disease and to develop drugs targeting this chemokine or its receptors." (PMID 38139161, 2023). "The elevated CCL5 concentration in patients with periodontitis may be related to the inflammatory response in the gingiva." (PMID 38139161, 2023). "The source of CCL5 in the gingiva of patients affected by periodontitis may be various cells that produce this chemokine in response to factors associated with this disease." (PMID 38139161, 2023). "In addition, we aim to stimulate interest in this relatively overlooked factor among periodontitis researchers, potentially accelerating the development of drugs targeting CCL5 or its receptors." (PMID 38139161, 2023). "The quoted data suggest that, in addition, CCL5 may also be involved in gingival infiltration by monocytes in periodontitis." (PMID 38139161, 2023). "This property suggests that CCL5 may inhibit bone degeneration in periodontitis, although further research is needed to investigate the exact effect of CCL5 on bone tissue in periodontitis." (PMID 38139161, 2023). "The results of studies in patients with chronic periodontitis are inconsistent as to whether and how cigarette smoking affects CCL5 production in the gingiva of patients with this disease." (PMID 38139161, 2023). "Treatment of both healthy and periodontally diseased gingival fibroblasts with pan-HDACi or HDAC3/6i prior to P. gingivalis infection significantly reduced the induction of a subset of inflammatory mediators (CCL2, CCL5, CXCL10, IL1B, COX2 and MMP3) implicated in periodontitis." (PMID 36291079, 2022). "Therefore, studies have shown that after periodontitis and periodontitis treatment, the concentration of CCL5 in the blood of patients remains at a high level." (PMID 34556089, 2021). "Besides periodontitis, IL-6, IL-8, and CCL-5 as major proinflammatory mediators they also play critical roles in many inflammation-related diseases, including osteoarthritis and Parkinson’s disease." (PMID 27529418, 2016). "Patient characteristics may be factors influencing CCL5 expression in periodontitis." (PMID 38139161, 2023). "The study revealed that allele A, rather than allele G, was more prevalent in CCL5-403 in generalized aggressive periodontitis (GAgP) patients, with a rate 3.7 times higher than in chronic periodontitis (CP) patients and 2.0 times higher than in chronic gingivitis (CG) patients." (PMID 37927745, 2023).
periodontitis (continued). "Not all bacteria that cause periodontitis increase the expression or production of CCL5." (PMID 38139161, 2023). "However, a study on British and Swedish patients has shown that CCR5Δ32 polymorphisms and CCL5 A/G polymorphisms are not correlated with the incidence of chronic periodontitis." (PMID 38139161, 2023). "Moreover, chemokines such as CXCL8, CXCL10, CXCL12, and CCL5 accumulate in the crevicular fluid of periodontitis patients and their source might be attributed to fibroblasts at least for CXCL2, CXCL3, CXCL8, CXCL9, CXCL10, CXCL12, and CXCL16." (PMID 37762294, 2023). "In the process of periodontitis, chemokines such as CXCL-8, CXCL-1, and CCL-5 and cytokines such as TNF-α, IL-1β, and IL-6 are present, due to the action of these multi-factors, it progresses to severe periodontitis with loss of periodontal support structures." (PMID 40733170, 2025). "Periodontitis and CKF show genetic cross-talk, which is supported by five hub genes, i.e., CCL5, FCGR3B, MMP-9, SAA1, and SELL." (PMID 37510279, 2023). "To confirm the inflammatory conditions within periodontitis gingiva, we observed up-regulation of SDF-1, CCL5, IL-1α, IL-4, and other inflammatory cytokine genes by qPCR." (PMID 36991451, 2023). "The induction of PDLSC migration by CCL5 results in PDLSC homing to sites involved in inflammatory responses, including those in periodontitis." (PMID 38139161, 2023). "Similar to CCL5, FCGR3B supports the link between periodontitis and CKF via increased pro-inflammation." (PMID 37510279, 2023). "BET inhibition significantly suppressed cytokine-induced mRNA expression of a broad range of inflammatory mediators involved in the pathogenesis of periodontitis, including IL8, IL1B, CCL2, CCL5, MMP3, and COX2." (PMID 31114581, 2019). "MIP-1α/CCL3, described as an osteoclast differentiation factor, and RANTES/CCL5, a chemotactic factor for these cells, are found in periodontitis tissues." (PMID 24151615, 2013). "At the same time, there are also studies suggesting that blood levels of CCL5 do not differ between healthy individuals and patients with chronic periodontitis." (PMID 38139161, 2023). "The bacterium also increases CCL5 production in gingival mesenchymal stromal cells (GMSCs) from patients with periodontitis, an effect not observed in healthy individuals." (PMID 38139161, 2023). "These cells from people with periodontitis produce more CCL5 but less IL-12p70 in response to LPS, which suggests that the immune response of patients with periodontitis differs from that of patients without periodontitis." (PMID 38139161, 2023). "The same study also showed that cigarette smoking did not affect serum CCL5 levels in patients with chronic periodontitis." (PMID 38139161, 2023). "In conclusion, five hub cross-talk genes, i.e., CCL5, FCGR3B, MMP-9, SAA1, and SELL, could be involved in the interplay between periodontitis and CKF, whereby primarily inflammation, metabolic, and vascular issues appear to be of relevance." (PMID 37510279, 2023). "Despite its importance, there is currently no comprehensive review of the role of CCL5 in periodontitis in the literature." (PMID 38139161, 2023). "A study of patients with generalized chronic periodontitis showed that the ratio of Porphyromonas gingivalis in plaque did not significantly correlate with the amount of CCL5 in GCF." (PMID 38139161, 2023). "MiR-200c directly targets 3′ UTRs of IL-6, IL-8, interferon-related developmental regulator 1 (Ifrd1), and chemokine (C-C motif) ligand 5 (CCL-5), and downregulated their expression in human periodontal ligament, gingival fibroblasts, and the periodontium of periodontitis rats." (PMID 37525201, 2023).
periodontitis (continued). "Plasma CCL5 in patients with chronic periodontitis was not significantly correlated with probing pocket depth, clinical attachment level, or bleeding on probing." (PMID 38139161, 2023). "Another study showed that CCL5 concentrations in GCF were lower in smokers with periodontitis than in periodontitis patients who did not smoke cigarettes." (PMID 38139161, 2023). "Analysis of gingival tissue showed higher levels of CCL5 in smokers with chronic periodontitis compared to non-smokers with periodontitis." (PMID 38139161, 2023). "Similarly, the CCL pathway, which is known to augment the production of IFNG from the CCL5‒CCR1 interaction, was strongly upregulated in periodontitis patients, which supports the higher activity of INFG." (PMID 36329504, 2022). "In periodontitis, CCL5 may not contribute to the development of the disease but instead may inhibit its progression." (PMID 38139161, 2023). "The main immune cells expressing this receptor and infiltrating gingival tissue may include Th1 cells and macrophages, although the exact role of CCL5 in the recruitment of these cells has not been investigated in models of periodontitis." (PMID 38139161, 2023). "However, Porphyromonas gingivalis infection does not appear to significantly affect CCL5 production in gingiva affected by periodontitis in humans." (PMID 38139161, 2023). "The chemokine called (regulated upon activation, normally T-cell expressed and secreted) (RANTES/CCL5) has also been detected in both the periodontal tissue and the GCF of persons with periodontitis, and in higher amounts in active sites compared to inactive periodontitis sites." (PMID 24151615, 2013). "CD14+ monocytes secrete a variety of cytokines, including TNF-α, IL-1β, IL-6, IL-8, CCL2, CCL3, and CCL5, compared to CD14− cells from GCF in patients with periodontitis, which suggests that CD14+ monocytes may be a source of CCL5 in GCF and gingival tissue in patients with periodontitis." (PMID 38139161, 2023).
triple-negative breast carcinoma (31 papers, 2013 to 2025). An invasive breast carcinoma which is negative for expression of estrogen receptor (ER), progesterone receptor (PR), and human epidermal growth factor receptor 2 (HER2). "Association of 9 SNPs of the CCL5 and CCL5 signaling pathway with triple negative breast cancer risk." (PMID 31921621, 2019). "Tumor cell-secreted IL6 has been reported to induce CCL5 expression in lymphatic endothelial cells and accelerate metastasis in triple-negative breast cancer." (PMID 39996058, 2025). "For instance, ZNF451 interacts with SLUG, facilitating SLUG-mediated CCL5 transcription, thereby driving the development of triple-negative breast cancer." (PMID 39534688, 2024). "Emodin, an active anthraquinone derivative isolated from Rheum palmatum, inhibits liver metastasis of triple negative breast cancer cells in mice by decreasing the secretion of CCL5 in serum." (PMID 37709489, 2023). "In triple-negative breast cancer, CCL5 expression has also been correlated with residual tumor size and tumor infiltrating lymphocytes after neoadjuvant chemotherapy." (PMID 30990165, 2019). "Moreover, it has been described that PAI1 and CCL5 signaling in endothelial cells leads to increased metastasis in EMT-induced triple-negative breast cancer cells." (PMID 32344898, 2020). "It has been shown that in CM cells, clofarabine (Clo) induces GSDME-mediated apoptosis by activating T cell immunity through CCL5 and CXCL10, and FAK-mediated phosphorylation of GRB7 plays a key role in triple-negative breast cancer (TNBC) cell migration." (PMID 41216288, 2025). "Migration assays were performed to analyze the functional relevance of the CCL5/CCR1 axis and revealed a migration-promoting role of this specific interaction in triple-negative breast cancer cells." (PMID 37444610, 2023). "Among these proteins, we observed that the C-C motif chemokine ligand 5 (CCL5) represented a key regulator factor and mediated the effect of DHEA in reducing the motility of triple-negative breast cancer cells." (PMID 37175104, 2023). "The expression of CCL5 and its receptor CCR5 has been found to be elevated in many tumors, including triple-negative breast cancer." (PMID 34771505, 2021). "Recently, it has been shown that LSD1 inhibition in triple negative breast cancer cell lines induces expression of CD8+ T cell-attracting chemokines, including CCL5, CXCL9, and CXCL10." (PMID 32649682, 2020). "Previous study suggested that endothelial cells (ECs) enhance endothelial-mesenchymal transition (EMT)-induced triple-negative breast cancer (TNBC) cell metastasis through PAI-1 and CCL5 signaling." (PMID 31795964, 2019). "In addition, CCL5 was highly expressed in HER2-overexpressing and triple-negative breast cancer subtypes (P = 0.024)." (PMID 36033472, 2022). "Recent studies have shown that endothelial cells may promote triple-negative breast cancer cell metastasis via PAI-1 and CCL5 signaling." (PMID 32728493, 2020). "Our previous study also demonstrated that CCL5 could induce the formation of MDSC to promote tumor growth and metastasis in triple-negative breast cancer." (PMID 29991744, 2018). "Moreover, in triple negative breast cancer (TNBC), PAI-1-secreted by TNBC cells could stimulate the expression and secretion of CCL5 from endothelial cells, which then enhanced TNBC cells migration, invasion, and metastasis." (PMID 31170987, 2019).
Insulin resistance (30 papers, 2011 to 2025). Increased resistance towards insulin, that is, diminished effectiveness of insulin in reducing blood glucose levels. "The previous study shows that CCL5 gene expression is elevated in adipose tissue of obese mice and is associated with inflammation and the progression of insulin resistance in obese humans and mice, which is consistent with the results of this study." (PMID 40725440, 2025). "For example, mice with tissue-derived CCL5 deficiency were protected against adipose tissue inflammation and insulin resistance induced by a high-fat diet." (PMID 40725440, 2025). "Second, CCL5 deficiency enhances glucose tolerance in lean mice but deteriorate insulin resistance by upregulating T cell-mediated adipose inflammation in obese mice." (PMID 36713454, 2022). "Furthermore, CCR5 and CCL5 were associated with the mechanisms of insulin resistance in PCOS through increased serine phosphorylation and inhibition of Akt phosphorylation." (PMID 35008567, 2021). "Therefore, the increased hepatic steatosis in obese CCL5 KO mice may be caused not only by insulin resistance and inflammation but also by the loss of the direct influence of CCL5 on hepatocyte lipogenesis." (PMID 36713454, 2022). "CCL5 (encodes for C-C motif chemokine 5) has been shown to promote immunosuppression in humans and mice by attracting immunosuppressive T-cells and MDSC and exacerbating insulin resistance." (PMID 40589518, 2025). "Functionally, ANGPTL8 worsened insulin resistance and glucose intolerance in obese mice, effects that were reversed by its deletion and recapitulated by CCL5 administration." (PMID 41289013, 2025). "CCR5 and CCL5 were also significantly correlated with the homeostasis model assessment of insulin resistance (HOMA-IR)." (PMID 35008567, 2021). "A further study has been performed to investigate the mechanisms and relationship between CCR5 and CCL5 and insulin resistance." (PMID 35008567, 2021). "In support of this argument, TNF-α, IL-6, IL-8, CCL2, CCL4, CCL5, and CCL19 were found to be implicated with metabolic inflammation or insulin resistance in various tissues and organs." (PMID 31718015, 2019). "A previous study found that inflammatory macrophages release TNF-α, inducing insulin resistance in adipocytes, which then secrete more CCL5 and MCP-1 and attract more macrophages that infiltrate into adipose tissue." (PMID 28900399, 2017). "Third, CCR5 and CCL5 regulatory effects on insulin signaling in hypothalamus contribute to peripheral insulin resistance and glucose intolerance." (PMID 27898058, 2016). "Thus, it is not surprising that key proinflammatory cytokines, including TNF-a, IL-6, CCL2, and CCL5, which are present at high serum concentrations in patients with insulin resistance, are mediators of HSC activation." (PMID 37735474, 2023). "As adipose tissue dysfunction could promote the progression of hepatic steatosis due to insulin resistance and proinflammatory adipokines release, the heaven hepatic steatosis may ascribe to severe adipose tissue dysfunction in obese CCL5 KO mice." (PMID 36713454, 2022). "Therefore, whether hepatic steatosis triggers insulin resistance in obese CCL5 KO mice remains to be studied." (PMID 36713454, 2022). "Therefore, a reduced expression of CCL4 and CCL5 after administration of CR may decrease inflammation and ameliorate insulin resistance." (PMID 34360840, 2021). "The role of CCL5 in the mechanism and pathogenesis of insulin resistance is still unknown." (PMID 35008567, 2021). "• T cell activation. • Induction of inflammatory molecules like IL8, IL12A, CCL5, CCL19, CCR2, and CCR5. • Contribution to increased insulin resistance secondary to TLR2, TLR4, and TLR10 interaction." (PMID 35422689, 2022). "The present study focuses on investigation of the role and potential mechanisms of CCL5/RANTES and CCR5 signaling in energy metabolism regulation, glucose intolerance, and insulin resistance in the hypothalamus." (PMID 27898058, 2016).
Insulin resistance (continued). "In summary, our study showed how the inflammatory chemokine CCL5 and its receptor CCR5 contribute to insulin resistance and glucose metabolism in the hypothalamus." (PMID 27898058, 2016). "Adipose tissue-associated IL-2 is also associated with overexpression of a variety of inflammatory markers, such as IL-8, IL-12a, IL-1β, C-C motif chemokine ligand 5 (CCL5), CCL15, TLR2, and an inflammatory macrophage marker (CD11c), inducing inflammation and insulin resistance." (PMID 40863244, 2025). "On the other hand, via GPR75, RANTES/CCL5 stimulates insulin secretion from β-cell lines and mouse and human pancreatic islets in vitro, and improves glucose tolerance in lean mice and a mouse model of hyperglycaemia and insulin resistance without changing insulin sensitivity." (PMID 35628332, 2022).